NSMCE2 (NSE2 SUMO ligase component of SMC5/6 complex)
Description:
E3 SUMO-protein ligase component of the SMC5-SMC6 complex, a complex involved in DNA double-strand break repair by homologous recombination. Is not be required for the stability of the complex. The complex may promote sister chromatid homologous recombination by recruiting the SMC1-SMC3 cohesin complex to double-strand breaks. The complex is required for telomere maintenance via recombination in ALT (alternative lengthening of telomeres) cell lines and mediates sumoylation of shelterin complex (telosome) components which is proposed to lead to shelterin complex disassembly in ALT-associated PML bodies (APBs). Acts as an E3 ligase mediating SUMO attachment to various proteins such as SMC6L1 and TSNAX, the shelterin complex subunits TERF1, TERF2, TINF2 and TERF2IP, RAD51AP1, and maybe the cohesin components RAD21 and STAG2. Required for recruitment of telomeres to PML nuclear bodies. SUMO protein-ligase activity is required for the prevention of DNA damage-induced apoptosis by facilitating DNA repair, and for formation of APBs in ALT cell lines. Required for sister chromatid cohesion during prometaphase and mitotic progression.
Synonyms: C8orf36; MMS21; FLJ32440; NSE2; ZMIZ7
Tractability: PROTAC: UniProt records ubiquitination sites on it; ubiquitination databases record sites on it; its protein half-life has been measured.
Gene: Protein-coding gene on chromosome 8 (125,091,673 to 125,367,729, forward strand). Ensembl gene ENSG00000156831.
Subcellular location: Nucleus; Chromosome, telomere; Nucleus, PML body
Subcellular location (Human Protein Atlas): Nucleoplasm; Nuclear bodies
Pathways (Reactome):
Metabolism of proteins: SUMOylation of DNA damage response and repair proteins
Gene Ontology:
Molecular function: protein binding; SUMO transferase activity; SUMO ligase activity; zinc ion binding
Biological process: cellular senescence; double-strand break repair via homologous recombination; double-strand break repair via nonhomologous end joining; positive regulation of maintenance of mitotic sister chromatid cohesion; positive regulation of mitotic metaphase/anaphase transition; telomere maintenance via recombination; chromatin looping; protein sumoylation; regulation of telomere maintenance
Cellular component: chromosome, telomeric region; nuclear body; nucleoplasm; nucleus; PML body; Smc5-Smc6 complex
Genetic constraint (gnomAD): Loss-of-function variants: 1 observed, 4.22 expected, observed/expected ratio (o/e) 0.24, 90% interval 0.083 to 1.11. That is too few expected variants to judge how well the gene tolerates losing a copy. Missense variants: 73 observed, 95.71 expected, observed/expected ratio (o/e) 0.76, 90% interval 0.63 to 0.93. Synonymous variants: 27 observed, 29.78 expected, observed/expected ratio (o/e) 0.91, 90% interval 0.67 to 1.25.
Gene-disease validity (ClinGen):
ClinGen rates the evidence that NSMCE2 causes each of these diseases.
Seckel syndrome 10 (autosomal recessive): Moderate. Any Seckel syndrome in which the cause of the disease is a mutation in the NSMCE2 gene.
Homologues: Orthologues: chimpanzee NSMCE2 (100% identical), macaque NSMCE2 (91% identical), rabbit NSMCE2 (90% identical), dog NSMCE2 (88% identical), pig NSMCE2 (87% identical), guinea pig NSMCE2 (87% identical), rat Nsmce2 (85% identical), mouse Nsmce2 (84% identical), tropical clawed frog nsmce2 (47% identical).